IL2 (interleukin 2)
Diseases named in the same sentence as IL2 in open-access papers (continued):
Sharing a sentence is not in itself a finding about the gene and the disease.
tumor (continued). "SPP reduced TNF-α and IL-2 levels while increasing INF-γ levels in the serum of tumor-bearing nude mice." (PMID 37538184, 2023). "The excised tumor was fragmented or enzymatically digested, and subsequently, TILs were isolated and cultured in the presence of interleukin-2 (IL-2) to promote TIL proliferation." (PMID 37421109, 2023). "IL-2 plays a critical role in the activation of the immune system and has been shown to be capable of mediating tumor regression as a monotherapy, making it a potential way to eradicate cancer." (PMID 38011277, 2023). "Combination treatment also led to a significantly higher SIY-reactive CD8+ T cell/Treg ratio in tumor-bearing lungs compared with IL2-MSA alone." (PMID 37669107, 2023). "A modest tumor growth inhibition was observed in the mice treated with IL2-7NP2-TNFmut (p-value of 0.0145 at day 15)." (PMID 37092450, 2023). "By modifying the bacterial vectors to express cytokines and tumor antigens (TAs), such as IL-2 or mesothelin, they can induce targeted immune responses from T and NK cells that specifically recognize tumor cells." (PMID 37681891, 2023). "The relevance of IL-2 in potentiating anti-tumor activity of Tα1 in combination with cyclophosphamide was further evidenced in mouse model of Lewis lung carcinoma, where depletion of T cells abolished the positive response to combination therapy." (PMID 37529610, 2023). "For example, IL-2 is an inducer of Th9-cell differentiation and Th9-mediated IL-9 production, two factors correlating with better tumor cell survival and apoptosis resistance." (PMID 36839658, 2023). "The administration of resveratrol and IL-2 in humans and mice increased NK cell activity in the blood and effectively inhibited tumor growth and metastasis in mice." (PMID 36792722, 2023). "OSCSCs, serving as a poorly-differentiated tumor comparison, were lysed at higher levels by untreated and IL-2 stimulated primary NK cells in comparison to OSCCs." (PMID 37954598, 2023). "So far, little is known about the effects of IL-2 derivatives on tumor antigen-specific T cells and the phenomenon of T cell exhaustion, and the research to date appears controversial." (PMID 37045833, 2023). "This protein was created by fusing the N-terminus of pHLIP with the C-terminus of IL-2, allowing for selective delivery to the acidic tumor microenvironment due to the low pH insertion property of pHLIP, thereby reducing the side effects." (PMID 38067480, 2023). "Despite the considerable progress in cergutuzumab amunaleukin development, its IL-2-based applications are limited only by one tumor marker." (PMID 36839658, 2023). "More interestingly, Ad5/3-E2F-d24-hIL2 increased CD8+ T cells in the tumor microenvironment compared with systemic IL-2 administration." (PMID 36923404, 2023). "Single-agent olaparib increased IL-2 production (a key cytokine in anti-tumour immunity) in T cells, which also trended with good responders." (PMID 37365284, 2023). "To further evaluate the effector function of different CAR-T cells upon antigen-specific stimulation, we conducted a coculture assay to measure the release of cytokines (IFN-γ, TNF-α and IL-2) after incubation with tumor cells." (PMID 37777797, 2023). "OESO_0105 which displayed only IL-2 responses to tumour antigens, had high intra-tumoural CD8+ cells in pre-NAT samples, but low CD8+ infiltration following therapy." (PMID 37965317, 2023). "Nevertheless, it is likely that the addition of CD122-targeted IL-2 affects gene expression of the tumor-specific T cell subsets studied here." (PMID 37045833, 2023). "Electrotransfer of Control, IL-2 and IL-12 plasmids alone and their combination was performed to the tumours pre-treated with collagenase and hyaluronidase." (PMID 37629081, 2023). "Microencapsulation of IL‐2 with FPC2 allows a prolonged presence of IL‐2 within tumors, since IL‐2 is protected against proteases secreted by tumor cells and released in a controlled manner." (PMID 36684086, 2023).
tumor (continued). "Our data demonstrated LPS‐Nb36 treatment coupled with irradiated DC/HepG2, DC/A549, or DC/MGC-803 fusion cells contributed to an enhanced release of inflammatory mediators (TNF-α, IFN-γ, and IL-2) in contrast to the DC/tumor fusion groups (p < 0.001)." (PMID 37419930, 2023). "Mice were subcutaneously inoculated with CT26-IRFP tumor cells in the rib abdomen, and the tumor tissues were injected with PD-1v, IL-2/15, IL-12, and GM-CSF recombinant plasmids for treatment during the experimental period." (PMID 37199371, 2023). "Despite the rich presence of a cellular antigen, IL2-7NP2-TNFmut achieved a partial localization in the in vivo setting, failing to uniformly localize in the whole tumor section." (PMID 37092450, 2023). "Cytokines such as interleukin-2 (IL-2) and IL-12 have previously been introduced to increase intertumoral lymphocyte infiltration and anti-tumor immunity, but their production in response to ICIs can increase irAEs." (PMID 37210537, 2023). "Multifunctional CD8+ T cells, as the critical effector cells of protective immunity, can secrete various cytokines (IFN-γ, TNF-α, IL-2, etc.), playing an important role in the anti-tumor effect." (PMID 37542081, 2023). "Targeting PD-1 and PD-L1 showed good anti-tumor activity, along with less toxicity, than IL-2 therapy." (PMID 38139110, 2023). "This review seeks to address the key questions: How can we balance the dual roles of IL-2 to optimize its anti-tumor effects?" (PMID 37516849, 2023). "CD8+ T cell effector activity, proliferation, and recruitment to the tumor site are largely augmented by tumor-specific CD4+ T cells via IL-2 signaling." (PMID 38328405, 2023). "The nanoparticles increased the accumulation of IL-2 in the tumor, leading to improved antitumor activity." (PMID 37175653, 2023). "We conclude that low-dose interleukin-2 and tumor necrosis factor-a immunotherapy can mediate tumor regression while posing manageable harm." (PMID 36874133, 2023). "When this combination was administered to an in vitro model of the tumor and interleukin (IL)-2 was added, an expansion in the number of tumor-specific CD8+ T cells and an improvement in the multifunctionality of pro-inflammatory cytokines were observed." (PMID 37152280, 2023). "Repeated intratumorally injected IL-2 has mediated tumor regression through an endogenous, tumor-specific in vivo CTL response and reduced vasculature in a murine model of mesothelioma." (PMID 38006049, 2023). "By comparing the co-administration of DTIC/Lipo-SM/Chol and Epacasome-2 or monotherapy alone, we elucidated that DTIC/Epacasome-2 induced noticeably higher tumour-infiltrating levels of IL-2, especially in combination with α-PD-1." (PMID 37945606, 2023). "These first-generation CARs were able to specifically recognize and kill tumor targets as well as produce interleukin-2 (IL-2) in vitro; however, they are unsuitable for clinical application due to their suboptimal persistence and anti-tumor activity." (PMID 37370693, 2023). "Consistently, PC significantly increased the efficacies of IL-2 or IL-2 plus PD-1 blocking antibody on tumor suppression and overall survival of mice." (PMID 37932447, 2023). "Together with the reduction in the volume and weight of tumor, this plant extract increased the level of IL-2 in the bloodstream and reduced those of IL-6 during metastasis formation." (PMID 36768978, 2023). "Although IL-2-based therapies have exhibited promise in some cancer types, the complex interplay between IL-2 and the tumor microenvironment necessitates further investigation." (PMID 37516849, 2023). "Thereafter, an in vivo analysis revealed an inverse correlation between IL-2 levels and tumor size, i.e., mice with higher levels of IL-2 had a much slower tumor growth." (PMID 36983053, 2023). "SPP significantly reduced TNF-α and IL-2 in tumor-bearing nude mice in our experiments, implying that SPP improves the serum inflammatory response in nude mice." (PMID 37538184, 2023).
tumor (continued). "Bulk tumor samples were stimulated ex vivo with cytokines with defined roles in antitumor immunity (interleukin-2 [IL-2], IL-6, and interferon-α [IFN-α])." (PMID 37192001, 2023). "These NPs proficiently delivered the hydrophobic DOX and hydrophilic interleukin-2 to attain the combination therapy against the tumor microenvironment." (PMID 38202616, 2023). "This intriguing finding suggests that the co-administration of CU06-1004 with IL-2 not only maintains the tumor suppression effect of IL-2 but also potentially enhances it." (PMID 37711172, 2023). "In this context, the levels of GM‐CSF, TNF‐α, IFN‐γ, IL‐1β, IL‐2, IL‐4, IL‐6, IL‐10, and IL‐13 in the peripheral blood of H22 tumor‐bearing mice were detected." (PMID 36043445, 2023). "IL-10 is an anti-inflammatory cytokine that plays a crucial role in tumor killing and inhibits the production of IFNg, IL-2, IL-3, and TNFα." (PMID 37445686, 2023). "5FU/IL2/CD2 nanoplexes achieved better histopathological values considering primary tumor foci and the mean number of metastatic foci." (PMID 36839637, 2023). "In a cancer setting, CD4+ T cells orchestrate anti-tumor immune responses by activating CTLs in tumors via production of IL-2 and IFN-γ." (PMID 36005179, 2022). "TILs are collected from patient’s tumor, expanded ex-vivo in the presence of recombinant IL-2, to improve the anti-tumor cytotoxic function showing objective tumor shrinking in several types of cancer including metastatic melanoma." (PMID 36428811, 2022). "These CAR-Ts also mediated IL-2 production and secretion and specific cytotoxicity upon target tumor cell engagement." (PMID 35468841, 2022). "In contrast, tumors treated with CAR T cells containing the synthetic autocrine IL-2 circuit showed substantially increased infiltration of T cells throughout the tumor core (bottom)." (PMID 36520915, 2022). "Granulocyte-macrophage colony-stimulating factor (GM-CSF) and IL-2 are the most potent cytokines for the induction of tumor-specific systemic immune responses." (PMID 36159788, 2022). "When assessing immunological factors contributing to our observed tumor control, significantly enhanced T cell population with superior effector function was observed in mice treated with Salmonella + Alb-IL2." (PMID 35962391, 2022). "More than half of the mice treated with both Pmel-1 and IL-2 displayed well-controlled tumor growth until 20 days." (PMID 36497152, 2022). "NK cells are responsive to the primary cytokine IL-2 in the tumor microenvironment (TME), to activate its effector functions against tumors." (PMID 34999917, 2022). "Treatment of tumor-bearing mice with Salmonella + Alb-IL2 leads to superior tumor control and enhanced overall survival compared to controls." (PMID 35962391, 2022). "Yet, the high doses of IL-2 required for tumor regression are commonly accompanied by severe side effects, such as vascular leak syndrome." (PMID 36591309, 2022). "We found that nearly half of the tumor-infiltrating live cells were Pmel-1 in the TBI/IL-2 combination group." (PMID 36497152, 2022). "The kinetics and toxicity of exogenously administered IL2 would be expected to be very different than that of IL2 produced in the tumor microenvironment by resident T cells." (PMID 34110453, 2022). "IL-2 is a noted anti-tumor factor, low dose of which presented the ability of enhancing the antibody-dependent cellular cytotoxicity (ADCC) effect, as well as the cytotoxic effect mediated by immuno-conjugate molecule (hI-con1) to USPC cells." (PMID 36531027, 2022). "When analyzing the fluorescence activity, Alb-IL2 demonstrated preferential trafficking to the tumor tissue." (PMID 35962391, 2022). "As a multifunctional cytokine, IL-2 shows suppressing or promoting effects on tumor via regulating the propagation and function of natural killer (NK) cells or T cells." (PMID 36531027, 2022).
tumor (continued). "CT26 tumor-bearing BALB/c mice received three doses of T cell depleting antibodies while being administered Alb-IL2 and Salmonella, as indicated in the schematic." (PMID 35962391, 2022). "Lower expression level of IL-2 in the high-Metabolism Score group compared with low-Metabolism Score group, which indicates less effective T cells and worse anti-tumor response in high-Metabolism Score subgroups." (PMID 35812404, 2022). "It is based on inducing immune responses, e.g. by infusing monoclonal antibodies against the tumor-associated disialoganglioside GD2, combined with for example granulocyte–macrophage colony-stimulating factor and interleukin-2." (PMID 36037157, 2022). "Our experiments revealed that at least two signals were necessary to overcome unresponsiveness of tumor-derived NK-cells in GBM: Firstly, tumor-derived NK need to be preactivated by IL-2 stimulation." (PMID 35474089, 2022). "Even with a reduced IL-2 dose and frequency, i.t. administration of nanobody–IL-2 fusions to B16F10 tumors markedly reduced tumor growth and led to a more pronounced benefit from enhanced affinity for EIIIB." (PMID 36712341, 2022). "Early studies using vaccines with irradiated whole tumor cells alone were unsuccessful; however, using several cytokines such as interleukin-2 (IL-2) or granulocyte-macrophage colony stimulating factor (GM-CSF) increased the efficacy of whole cell vaccines." (PMID 35632496, 2022). "This study provides clear evidence illustrating the fundamental role of IL-2 and IL-2 receptors in the anti-tumor efficacy of CTLA-4 blockade." (PMID 35392976, 2022). "The interaction between programmed cell death protein (PD-1) and programmed cell death ligand (PD-L1) inhibited T cell activity and the release of IFN-γ and IL-2, which produced a temporary immunosuppressive signal to reduce anti-tumor response ability." (PMID 36249790, 2022). "The most essential cytokines in the anti-tumour response are IL-12, granulocyte-macrophage colony-stimulating factor GM-CSF, T cell growth factor IL-2, IL-2-related cytokines IL-15 and IL-21 and pro-inflammatory IFNγ and TNFα." (PMID 36140243, 2022). "We evaluated the accumulation of CD8+MP and Tregs on the spleens of tumor-bearing mice treated with IL-2 or mutein on day 21 after tumor implant." (PMID 36059465, 2022). "Combination therapy for the herpes simplex virus type 1 (HSV-TK) genes and the IL-2 coding genes was well tolerated in recurrent GBM patients with 50% tumor responses." (PMID 36146527, 2022). "For the first time, the correlation of salivary levels of TNF-α, IL-1β, and IL-6 with HER2 status, MCP-1, IL-1β, IL-2, and IL-4 with the hormonal status of the tumor was shown." (PMID 36286034, 2022). "Another study demonstrated that the combination of CAR-T cells and modified OVs expressing TNF-α and IL-2 has a robust anti-tumor effect in the pancreatic ductal adenocarcinoma (PDA) murine model." (PMID 36419058, 2022). "Our group demonstrated that incubation of NK cells with the Hsp70 protein or the Hsp70-derived peptide “TKD”, together with the pro-inflammatory cytokine IL-2, stimulates their cytolytic activity against membrane Hsp70-positive tumor cells." (PMID 36428793, 2022). "In fact, tumor-related CD4+ T cells spontaneously produce IL-2, a cytokine essential for the development and activation of Tregs." (PMID 36068484, 2022). "Although NK cells are considered prototypical cytolytic anti-tumor effectors, when exposed to IL-1β, IL-23 and IL-2, ILC3s induced significantly higher cancer cell lysis compared to NK cells." (PMID 35300331, 2022). "By varying these two attributes, we systematically alter the local pharmacokinetic features of IL-2 fusion proteins and define how each interact to impact local retention and anti-tumor efficacy in mice." (PMID 35013154, 2022).
tumor (continued). "The TIL-ACT process begins by isolating the natural infiltrating lymphocytes from the tumor tissues, expanding them in vitro, and then infusing these cells with a high dose (HD) of IL-2 into patients to identify and kill tumor cells." (PMID 36077696, 2022). "They showed that adding ICIs before and during TIL infusion with low-dose IL-2 resulted in manageable toxicity and sizeable tumor regressions." (PMID 36389779, 2022). "This therapy involves the extraction of tumour-infiltrating lymphocytes from tumour resections, which are then expanded ex vivo with the use of Interleukin-2 producing a product that can be infused back into the same patient." (PMID 35804876, 2022). "The activation of infused CAR T cells and interaction with tumor cells leads to the release of several cytokines including IL-2, soluble IL-2Rα, IFNγ, IL-6, tumor necrosis factor (TNF)-α, soluble IL-6R, and GM-CSF." (PMID 35845425, 2022). "Cytokines, such as IFN-γ, TNF-α and IL-2, produced by Th1 cells were found to be vital factors in the inhibition of tumor growth." (PMID 35688915, 2022). "Because an autocrine circuit cell contains both the CAR and synNotch→IL-2 circuit, it has the capability to become both a preferred IL-2 responder (via T cell activation) and strong IL-2 producer (via synNotch activation) within a tumor." (PMID 36520915, 2022). "Both approaches effectively reduced galanin in the CM and enhanced the proliferation of PBMCs, indicating that tumor-secreted galanin plays a relevant role in the inhibition of IL-2/mitogen-induced proliferation of immune cells." (PMID 35267186, 2022). "To selectively deliver IL-2 to PD-1+CD8+ tumor-infiltrating lymphocytes (TILs), we engineered a low-affinity IL-2 paired with anti–PD-1 (PD-1–laIL-2), which reduced affinity to peripheral Treg cells but enhanced avidity to PD-1+CD8+ TILs." (PMID 35104810, 2022). "Strategies incorporating IL-2 into ex vivo expansion protocols have been investigated for immune cells, such as tumor-infiltrating T (TILs), CAR-T, and NK cells, to promote their activation and proliferation." (PMID 35806311, 2022). "And the fusion protein IL2-GMCSF has been studied to enhance IL-2 and GM-CSF levels to interfere with tumor immune response." (PMID 36159788, 2022). "It was proclaimed that the killer cells activated by IL-2 have a capacity to distinguish normal endometrial cells from malignant endometrial cells, which made it prospective for IL-2 acting as an anti-tumor cytokine." (PMID 36531027, 2022). "Here, we show that CAR engineering of NK-92 cells overcomes the IL-2 dependence and restores their anti-tumor cytolytic activity." (PMID 35287669, 2022). "Recombinant IL-2 has also been evaluated at a low dose to limit its toxicity to support tumor vaccines." (PMID 35651800, 2022). "Both the systemic and the intracerebral infusion of IL-2/Hsp70-treated NK cells led to the shrinking of the tumor to almost undetectable levels 8 days after treatment (p = 0.0029 and p = 0.0319, respectively), while non-activated NK cells were ineffective." (PMID 35203609, 2022). "This obstacle, together with the low rates of anti-tumor response, has limited the immunotherapeutic administration of IL-2 as monotherapy." (PMID 36231109, 2022). "Here, by evaluating different IL-2 fusion proteins, the authors show that molecular weight and matrix binding affect anti-tumor immune response and report a pharmacokinetic framework to predict response to intratumoral IL-2 therapy." (PMID 35013154, 2022). "Why does the autocrine IL-2 induction circuit perform so much better than the equivalent paracrine circuit in driving T cell infiltration of immunosuppressed tumor models?" (PMID 36520915, 2022).